PNPLA3 (patatin like domain 3, 1-acylglycerol-3-phosphate O-acyltransferase )
Diseases named in the same sentence as PNPLA3 in open-access papers (continued):
Sharing a sentence is not in itself a finding about the gene and the disease.
steatosis (continued). "Recently, a missense SNP, Glu434Lys (rs2294918), was shown to lower the PNPLA3 protein level and protect against steatosis." (PMID 28950858, 2017). "PNPLA3 carriers showed higher steatosis, portal inflammation and HpSC niche activation compared to wild-type patients." (PMID 29150621, 2017). "The results from modeling within each of the three individual data domains were then used to create a multi-component classifier that included PNPLA3 genotype, steatosis clinical prediction score, and the proteomic classifier." (PMID 28266614, 2017). "In fact, we have demonstrated elsewhere that there is a relation between a downregulation of the lipogenic pathway and the severity of steatosis in a cohort of MO women, and also between the liver expression of PNPLA3 and the severity of steatosis." (PMID 29065180, 2017). "Polymorphisms in genes that modulate lipid deposition in hepatocytes such as patatin-like phospholipase domain-containing protein 3 (PNPLA3) and transmembrane six superfamily member 2 (TM6SF2) predispose people to steatosis." (PMID 28883965, 2016). "The main results of our study show that liver PNPLA3 expression is increased in NAFLD patients and is particularly associated to severity of steatosis." (PMID 27128907, 2016). "It is important to note that we have demonstrated a clear relationship between PNPLA3 and the degrees of SS, suggesting a direct correlation between PNPLA3 and the severity of steatosis." (PMID 27128907, 2016). "On the other hand, the steatosis grade was significantly higher in patients with PNPLA3 CG/GG and PARVB AG/GG than in those with PNPLA3 CC (P < 0.001) and PARVB GG (P = 0.001), respectively." (PMID 26352693, 2015). "When the PNPLA3 rs738409 was controlled for, the SOD2 was still associated with the degree of histological steatosis, and was an independent risk factor for advanced fibrosis." (PMID 26462272, 2015). "The current meta-analysis provided a systematic assessment of the association between the PNPLA3 rs738409 polymorphism and susceptibility to NAFLD, including its subtypes simple steatosis and NASH." (PMID 25791171, 2015). "The association between PNPLA3 148M/M and FPR was nearly significant in patients with steatosis grade 2–3 including subjects with ultrasonographic estimation of steatosis severity (p = 0.056)." (PMID 25171251, 2014). "The I148M (rs738409) genetic variant of patatin-like phospholipase domain-containing 3 gene (PNPLA3) is known to modulate hepatic triglyceride accumulation, leading to steatosis." (PMID 22724004, 2012). "Previous studies of the PNPLA3 I148M sequence variant in HCV infected individuals have reported an association between this variant and prevalence of steatosis, fibrosis, and cirrhosis." (PMID 22978414, 2012). "The PNPLA3 148M variant promotes MASLD through a macrophage-specific NF-κB–NACC1–RIPK3 axis that enhances necroptosis and inflammatory signaling, thereby exacerbating hepatocyte steatosis and HSC activation." (PMID 41564367, 2026). "Finally, in the validation cohort, we observed a pronounced PZ distribution of steatosis, inflammation, and fibrosis in I148M PNPLA3 subjects compared to WT, confirming the spatial data." (PMID 41684020, 2026). "The targeting of the PNPLA3 I148M variant in a mouse model using tri-antennary N-acetyl galactosamine (GalNAC3) conjugated with an antisense RNA oligonucleotide (ASO) decreased hepatic inflammation, steatosis and fibrosis." (PMID 40563253, 2025). "Importantly, PNPLA3 I148M sequesters ABHD5 away from PNPLA2 leading to steatosis and modifies TAG metabolism in an ABHD5-dependent manner." (PMID 39814233, 2025). "Previous work demonstrated that the I148M mutation is not a simple loss of function mutation, as knockout of PNPLA3 does not produce steatosis in mice." (PMID 39814233, 2025).
steatosis (continued). "The I148M substitution of PNPLA3 results in a reduction in lipase activity; however, whole body deletion of PNPLA3 does not cause steatosis, implying that I148M is not a simple loss of function." (PMID 39814233, 2025). "Additionally, Pnpla3 I148M mice subjected to a high-sucrose diet exhibit even higher levels of triacylglycerol and fatty acids, along with more pronounced steatosis." (PMID 40004054, 2025). "Another population‐based study from the NHANES III cohort confirmed the lack of impact of the PNPLA3 G variant on extrahepatic cancer‐related mortality in the entire cohort of 4814 subjects and in the subgroup of 1952 with steatosis." (PMID 39412170, 2025). "Indeed, PNPLA3 was associated with a higher risk for both steatosis and hepatic fibrosis, while TM6SF2 was primarily linked with steatosis and MBOAT7 with hepatic fibrosis." (PMID 38809396, 2024). "While the PNPLA3 genotype did not exhibit an association with the grade of steatosis, individuals with GG homozygosity had an increased likelihood of significant NASH activity and fibrosis." (PMID 37632067, 2023). "Finally, the effect of DAAs on steatosis is still unclear, as some data report its progression despite HCV eradication, especially in metabolically deranged patients and in PNPLA3 variants." (PMID 37999215, 2023). "Family history and genetics: Steatosis level is increased in people who are homozygous for the I148M variant of the patatin-like phospholipase domain-containing protein 3 (PNPLA3) allele compared to those who are not carriers of this." (PMID 36320966, 2022). "We observed that patients with steatosis (any grade) more frequently harbored the PNPLA3 G allele variant [57.6% vs. 16.7% (p = 0.09)] than nonsteatosis patients." (PMID 36110512, 2022). "Beyond KIV and the BCKA/BCAA ratio, we identified 2 additional amino acid–related factors associated with steatosis grade, as well as a long-chain acylcarnitine-related factor that was associated with the presence of NASH in carriers of the major PNPLA3 allele." (PMID 35797133, 2022). "The associations of KIV with steatosis grade and NASH, and the BCKA/BCAA ratio with NASH, were maintained when a multivariate statistical model that considered BMI, sex, age, HbA1c, ALT, AST, GGT, PNPLA3 Ile148Met genotype, and study batch was applied." (PMID 35797133, 2022). "The same pattern (association of PNPLA3 with steatosis and steatohepatitis but not with hepatic scarring in CHC patients) was also evident from another Caucasian study." (PMID 36028802, 2022). "Altogether, PNPLA3 p.I148M and TM6SF2 p.E167K variants may promote steatosis and steatohepatitis which may indirectly predispose to progression of liver scarring (fibrosis and cirrhosis)." (PMID 36028802, 2022). "That applies, for example, to a common variant (I148M) in the patatin-like phospholipase domain-containing protein 3 (PNPLA3) gene that encodes a protein involved in the lipid metabolism, which influences the severity of steatosis, steatohepatitis, fibrosis, and HCC risk in NAFLD as well as in ALD." (PMID 35160340, 2022). "We could thereby recapitulate a positive correlation of PNPLA3(I148M) with steatosis, inflammation, the amount of microgranulomas, ballooning and fibrogenesis." (PMID 36611868, 2022). "In addition, PNPLA3-I148M significantly worsened the severity of histological features of NASH including steatosis, hepatocellular ballooning and lobular inflammation (p< 0.001)." (PMID 34040583, 2021). "Whereas silencing PNPLA3 does not lead to a disease phenotype, overexpression of the mutant PNPLA3‐148M variant generally has accelerated steatosis and some inflammation but not steatohepatitis with fibrosis." (PMID 34040583, 2021). "In a study including 98 WD patients, PNPLA3 c.444C>G and early onset were linked to advanced steatosis, whereas hepatic copper concentration was not relevant." (PMID 34572285, 2021).
steatosis (continued). "However, in autoimmune hepatitis the effect of PNPLA3-I148M was seemingly unrelated to hepatic steatosis, suggesting alternative mechanisms of action." (PMID 33544287, 2021). "Similarly a genetic risk score including variants in PNPLA3, TM6SF2, HSD17B13 and GCKR found a significant association with steatosis, steatohepatitis and fibrosis in a large cohort of patients with histologically characterized NAFLD [53••]." (PMID 33544287, 2021). "PNPLA3 might therefore represent a good therapeutic target to control NAFLD-associated fibrosis, steatosis, and disease progression." (PMID 34685739, 2021). "Furthermore, the treatment of primary hepatocytes bearing PNPLA3 rs738409 (148M variant) results in lipid reduction, consistent with the alleviation of PNPLA3 148M-induced steatosis." (PMID 33036387, 2020). "PNPLA3 polymorphism (CC vs. CG/GG) did not reveal any significant correlation with iron and lipid parameters including neutral and polar lipids, grade of steatosis and fibrosis." (PMID 32680469, 2020). "In HSCs, conversely, the PNPLA3 I148M variant alters retinol secretion, potentially contributing directly to fibrogenesis and carcinogenesis, increasing the risk for cirrhosis and HCC development, independently of the predisposition to steatosis." (PMID 32340286, 2020). "Moreover, it has been reported that there is a higher effect of I148M PNPLA3 on steatosis severity in individuals consuming diets poor in vegetables." (PMID 32365683, 2020). "PNPLA3-I148M interacts with CGI-58 possibly to impair ATGL activity as the basis of steatosis." (PMID 31062641, 2019). "Recent studies have hypothesized a direct role for PNPLA3 in the activation of hepatic stellate cells, and this mechanism could be the basis for steatosis and fibrogenesis; however, further studies are needed in order to demonstrate this relationship." (PMID 30189691, 2018). "Interaction between the IFNL3 and PNPLA3 genotypes in the pathogenesis of steatosis." (PMID 28797039, 2017). "In a GWAS, Romeo and colleagues first described the non-synonymous variant I148M of PNPLA3 as the strongest determinant of liver fat deposition, independent of ethnicity and other known risk factors for steatosis." (PMID 28629152, 2017). "Moreover, the variant showed an additive effect with PNPLA3 and Transmembrane 6 Superfamily Member 2 (TM6SF2) SNPs in determining the risk for steatosis." (PMID 28629152, 2017). "Like PNPLA3-148M, the TM6SF2-167K variant is associated with not only NAFLD but also alcoholic fatty liver disease and with the full spectrum of both disorders, extending from steatosis to cirrhosis (15, –, 19)." (PMID 27013658, 2016). "They showed a dissociation between hepatic de novo lipogenesis and liver fat content due to the PNPLA3 148M allele, suggesting that increased de novo lipogenesis is not a main feature in all subjects with steatosis." (PMID 27128907, 2016). "Among these, the rs738409 C>G (I148M) variant of the patatin like phospholipase domain containing 3 (PNPLA3) gene located at 22q13 is the most well validated association, influencing degree of steatosis, grade of inflammation, stage of fibrosis and risk of HCC." (PMID 27744419, 2016). "In contrast, the PNPLA3-I148M knock-in mice did not develop steatosis unless they were placed on a high sucrose diet, which causes an increase in hepatic fatty acid synthesis and PNPLA3 levels." (PMID 27013658, 2016). "In our samples, the PNPLA3 mRNA level was neither associated with NAFLD nor with the degree of steatosis." (PMID 27744419, 2016). "The mechanism underlying the association between a PNPLA3 gene polymorphism with the progression of steatosis, fibrosis, and development of HCC has not been determined." (PMID 25713769, 2015). "Steatosis maintained by the PNPLA3 genotype I148M may promote the progression of fibrosis and development of HCC." (PMID 25713769, 2015).
steatosis (continued). "The results showed the variant to be associated with severity of all histological characteristics (steatosis, necroinflammation, ballooning and fibrosis stage), and this persisted after adjustment for age, gender, BMI, diabetes, recruitment and PNPLA3 genotype." (PMID 26462272, 2015). "The I148M polymorphism results in a critical amino acid change next to PNPLA3’s catalytic domain, likely reducing substrate access and reducing enzymatic activity towards glycerolipids, thereby leading to the development of macrovescicular steatosis." (PMID 25290313, 2014). "In the overall series of patients including those with ultrasonographic estimation of steatosis, PNPLA3 148M/M (estimate +0.07±0.03, p = 0.033) and the interaction with older age at infection (estimate +0.07±0.03, p = 0.036) remained significantly associated with FPR." (PMID 25171251, 2014). "Of note, we reported for the first time an effect of 148M/M on fibrosis progression in genotype 3 patients, even if previous studies did not detect an association between PNPLA3 and steatosis in this subgroup." (PMID 25171251, 2014). "The negative impact of PNPLA3 148M/M on fibrosis progression was more marked in subjects at risk of altered hepatic lipid metabolism (those with grade 2–3 steatosis, genotype 3, and overweight; p<0.05)." (PMID 25171251, 2014). "The association between IL28B genotype and steatosis was independent of acquired risk factors, and of the PNPLA3 GG genotype." (PMID 23394097, 2013). "Genetic factors, and in particular the I148 M variant of Patatin-like phospholipase domain containing-3 (PNPLA3), play a major role in determining individual susceptibility to develop steatosis or NASH and progressive liver disease, interacting with dietary factors." (PMID 24282628, 2013). "In fact, even though steatosis has been widely reported to be associated with PNPLA3 148M allele, only a non-significant trend towards higher prevalence of steatosis was observed among PNPLA3 148M allele carriers in both HCV genotypes in the present study." (PMID 22978414, 2012). "A trend, although non-significant, towards a higher prevalence of steatosis was observed in PNPLA3 148M allele carriers in both HCV genotype 2 and 3 subjects." (PMID 22978414, 2012). "At logistic regression analysis, low adiponectin levels were associated with male sex, younger age, and steatosis, but not with PNPLA3 and ADIPOQ genotypes." (PMID 22898488, 2012). "The I148M polymorphism of Patatin-like phospholipase domain-containing 3 (PNPLA3), influences hepatic triglycerides accumulation and the susceptibility to fibrotic NASH in adults and children, steatosis susceptibility and liver damage progression in CHC, and progression to hepatocellular carcinoma." (PMID 22898488, 2012). "In contrast, in CHC, characterized by adiponectin resistance, low adiponectin was associated with male gender and steatosis, but not with PNPLA3 and ADIPOQ genotypes and viral features." (PMID 22898488, 2012). "This is in line with previous data showing an association between the PNPLA3 I148M genotype and steatosis in the HCV genotype 2 but not in the HCV genotype 3 infected subjects." (PMID 22978414, 2012). "After the demonstration that PNPLA3 p.I148M protein accumulates on LDs due to resistance to ubiquitylation and that this is necessary for the phenotypic expression of steatosis, we hypothesised that targeting mutant PNPLA3 for silencing may represent a therapeutic approach in carriers." (PMID 40747912, 2025). "Furthermore, when comparing across five steatosis‐associated genetic variants, only PNPLA3 I148M yielded a notably higher AUROC." (PMID 40478199, 2025). "Finally, PNPLA3 I148M targeting to LD is required to promote steatosis in vitro and in the liver." (PMID 39814233, 2025).
steatosis (continued). "Moreover, neither TG synthesis nor phosphatidic acid turnover were increased in the presence of the PNPLA3 variant in transgenic mice, indicating that an increase in acylglycerol transacylase activity is not responsible for the observed steatosis." (PMID 39000384, 2024). "The SNP of the patatin-like phospholipase domain-containing protein 3 (PNPLA3) gene's I148M variant is implicated in NAFLD, showing associations with reduced de novo lipogenesis, increased expression of SREBP-1c, and higher risks of steatosis and liver fibrosis." (PMID 39617908, 2024). "Genetic variations in Patatin-like phospholipase domain-containing protein 3 (PNPLA3), transmembrane 6 superfamily 2 (TM6SF2) or other genes associated with steatosis could possibly explain the association between lean NAFLD and the increased risk of future development of severe liver disease." (PMID 38405152, 2024). "In examining the genetic information available among patients in the cohort, we observed that for both lean patients and overweight patients, homozygous carriers of the PNPLA3 rs738409 variant were more prevalent among those with steatosis than among those without steatosis." (PMID 38167550, 2024). "Therefore, the more pronounced ER stress activation and lipoapoptosis seen in 148M/M cells than 148I/I cells in the present study may be attributed to higher accumulation on LDs and more pronounced hepatocyte steatosis in PNPLA3 148M/M." (PMID 36825197, 2023). "Notably, Pnpla3-KO did not cause steatosis phenotype in mice model, highlighting the interspecies difference in disease modeling." (PMID 37009924, 2023). "Interestingly, PNPLA3 carriers have a significantly increased risk of cirrhosis and hepatocellular carcinoma, independent of the tendency to steatosis." (PMID 35154322, 2022). "Moreover, PNPLA3 rs738409 non-CC genotype displayed strong association with steatosis progression after SVR." (PMID 35696400, 2022). "Likewise, Huang and colleagues demonstrated a role of PNPLA3 variant in HCV induced steatosis but no independent association with liver fibrosis and cirrhosis based on 1080 CHC patients of Chinese ancestry." (PMID 36028802, 2022). "Interestingly, Pnpla3 knockout mice do not develop steatosis; therefore, it appears unlikely that loss of hydrolytic activity is a sufficient explanation for the induction of steatosis." (PMID 36611868, 2022). "For instance, several single nucleotide polymorphisms (SNPs) such as patatin-like phospholipase domain-containing protein 3 (PNPLA3), transmembrane six superfamily member 2 (TM6SF2) and membrane bound O-acyltransferase domain-containing 7 (MBOAT7) appear to be associated with steatosis progression." (PMID 35696400, 2022). "A 2011 study compared two groups of Italian patients with HCV infection and indicated for the first time that PNPLA3 genetic variants influence steatosis development regardless of age, sex, body mass index, diabetes mellitus, alcohol consumption and viral genotype." (PMID 34833371, 2021). "Intriguingly, PNPLA3 mutated protein may impair retinol release from HSCs, directly precipitating fibrogenesis and carcinogenesis irrespective of steatosis." (PMID 34680476, 2021). "Besides PNPLA3 and TM6SF2 variations, the common loss-of-function rs1260326 variant in the GCKR gene, encoding the p.P446L substitution, has been widely associated with increased fasting TG concentrations, steatosis and liver damage." (PMID 32340286, 2020). "Further than the PNPLA3 and the TM6SF2 SNPs, we therefore tested the rs3750861 KLF6, the rs13412852 LPIN1, and the rs4880 SOD2 SNPs, which have demonstrated associations with fibrosis, steatosis and fibrosis, and again fibrosis, respectively, in previous studies on NAFLD patients." (PMID 29732362, 2018).